XIAP (X-linked inhibitor of apoptosis)
Diseases named in the same sentence as XIAP in open-access papers (continued):
Sharing a sentence is not in itself a finding about the gene and the disease.
cancer (continued). "One mechanism by which cancer cells escape apoptosis is the overexpression of antiapoptotic genes, particularly of BCL2, Bcl-xL, XIAP and survivin." (PMID 22797576, 2012). "XIAP and other proteins from the IAP family are attractive targets for anti-cancer drug design due to their elevated expression in cancer cells and their association to chemo-resistance." (PMID 21949740, 2011). "Sensitivity of XIAP depleted HCT-116, SW-620 and PC-3 tumor cells to various mechanistically distinct anti-cancer agents." (PMID 20067634, 2010). "The present study further demonstrates that regulation of XIAP expression by TGF-β isoforms impacts XIAP function in cancer cells, since each TGF-β isoform promotes XIAP-dependent degradation of PTEN when added exogenously." (PMID 20712893, 2010). "Moreover, upregulation of XIAP expression has been found to result in apoptosis resistance after exposure to anticancer drugs and ionising radiation, whereas downregulation of XIAP by antisense vectors increased the apoptosis sensitivity of carcinoma cell lines." (PMID 15328523, 2004). "Currently, the expression profile of XIAP in the progression of residual cancer tissue after IMWA has not been reported, and the effect of XIAP in the progression of residual cancer tissue is not clear." (PMID 39917292, 2025). "Because XIAP overexpression correlates strongly with cancer progression and chemoresistance, small-molecule XIAP antagonists and SMAC mimetics have been developed to inhibit the interaction between XIAP and these caspases to kill malignant tumor cells." (PMID 40533441, 2025). "Targeting the BIR2 and BIR3 domains of XIAP and other IAPs, there are several SMAC mimetics in clinical trials, including AT406, TL32711 (birinapant), LCL161, AEG40826, CUDC427, and others to release active CASP3 and CASP9 to kill cancers." (PMID 40533441, 2025). "Embelin cotargets SHP2 to disrupt the SHP2/GRB2/SOS complex, inhibiting cancer‐related signaling pathways such as MAPK, (PI3K)/AKT pathway, and XIAP to induce apoptosis signaling pathway, respectively, leading to synthetic lethality in KRAS‐mutant NSCLC cells both in vivo and in vitro." (PMID 39992860, 2025). "In addition, the knockdown of both XIAP and SHP2 reduced the migration and invasion abilities of cancer cells and decreased the expression of EMT marker proteins." (PMID 39992860, 2025). "Our data showed that those cancer cell lines with higher levels of XIAP:CASP7 (e.g. MCF-7, BT-483, MDA-MB-468, and ZR-75-1) were hypersensitive to 643943, consistent with that 643943 disrupts the XIAP:CASP7 complexes." (PMID 40533441, 2025). "Still, the biological relevance of this selectivity is not yet completely clear, as both XIAP and cIAP 1/2 are relevant in preclinical models of cancer." (PMID 37686191, 2023). "IAPs, including XIAP and cIAP1/2, have been shown to be frequently overexpressed in various cancers, including SCCHN, and increase the resistance of cancer cells to apoptosis and prevent cell death induced by anticancer treatments, such as chemotherapy and radiotherapy." (PMID 36640618, 2023). "XIAP also induces proinflammatory signaling by involving receptor-interacting serine/threonine kinase 2 (RIPK2) and production of interleukin 8 (IL-8) which leads to neutrophil recruitment in cancer and during infection." (PMID 36472768, 2023). "Compared to VHL, XIAP, and AHR, which were highly expressed in less than half of cancer types in TCGA, PHF14 may serve as a good candidate for pan-cancer usage over co-opted E3 ligases in terms of expression pattern." (PMID 37845222, 2023).
cancer (continued). "In addition, XIAP and MCL1 are antiapoptotic proteins that are overexpressed in several types of cancers and whose expression is regulated by MNK1." (PMID 37111758, 2023). "Given that XIAP is a negative regulator of apoptosis in cancer cells and is a direct target of miR-137 in GBM cells, we hypothesized that a miR-137-XIAP axis could play a functional role in regulating sensitivity of GBM cells to TRAIL-induced cell death." (PMID 35965517, 2022). "All the data showed that there is a general negative correlation between miR-137 and XIAP in cancer samples." (PMID 35965517, 2022). "Moreover, another IAP inhibitor, DEBIO1143 promotes apoptosis of cancer cells by mimicking the structure and activity of SMAC, which can block the XIAP and reactivate the caspase-9." (PMID 34026617, 2021). "Through the AKT-GSK3β-β-catenin and XIAP-Survivin pathways promoted by CCT-β, cancer cells could gain chemoresistance and metastasis." (PMID 33371405, 2020). "Since survivin, XIAP, TAB1 and TAK1 are involved in the anticancer effects of Sur-X, it can be inferred that Sur-X may have broader efficacy in cancer patients with high expression of survivin, XIAP, TAB1 and/or TAK1." (PMID 32381104, 2020). "For example, BIRC2 was clustered with BIRC3, XIAP and BIRC6 in more than 50% of the cancers." (PMID 31964418, 2020). "Currently, eight human IAPs have been identified: XIAP; cIAP1; cIAP2; ILP2; BRUCE/Apollon; survivin; NAIP; and ML-IAP, and targeting a subset of these proteins has been demonstrated to promote apoptosis in cancer cells." (PMID 33205060, 2020). "To analyze whether MDA-MB-231 and CL1-5 cell metastasis could be regulated by CCT-β through XIAP and β-catenin, we knocked down CCT-β from these two highly metastatic cancer cells." (PMID 33371405, 2020). "Using the Genomics of Drug Sensitivity in Cancer (GDSC) database for drug sensitivity and gene expression, we identified 8 drugs targeting the apoptosis pathway involving targets of BCL-2, BIRC5, Procaspases, RIPK1, TRAIL, and XIAP." (PMID 31964418, 2020). "In triple negative breast (TNBC) cancer cell lines, HHT was demonstrated to strongly decrease survival influenced by MCL-1, BCL-2, SURVIVIN, XIAP and could reduce cancer growth of MDA-MB-231 xenografts." (PMID 32151059, 2020). "Although the mechanisms of how XIAP was increased in cancers is not known, preliminary studies have shown it can be expressed by transcription factors such as NF-κB." (PMID 33138314, 2020). "The appeal of XIAP as a therapeutic target in cancer is not restricted to inhibition of apoptosis, but comprehends the regulation of other cellular physiological aspects, such as control of caspase-independent cell death." (PMID 31505859, 2019). "These drugs may upregulate the expression of DRs and FADD or downregulate anti-apoptotic proteins such as c-FLIP, XIAP or Survivin to enhance the effect of TRAIL and induce apoptosis of cancer cells." (PMID 31864387, 2019). "In addition to Smac mimetic, XIAP can also be targeted using antisense oligonucleotides (ASO), which was demonstrated to be potent against several cancers either as a single agent or in combination with conventional chemotherapeutics." (PMID 31652776, 2019). "XIAP, the most potent anti-apoptotic IAP, blocks apoptosis by inhibiting the activation of caspase-3, -7, and -9 and its dysregulation is commonly found in pediatric cancers." (PMID 31652776, 2019). "Furthermore, AKT activation contributes to evasion of apoptosis through inducing anti-apoptotic proteins such as C-FLIP, XIAP, and MCL-1 inhibited apoptotic signaling transduction in cancer cells." (PMID 31905887, 2019). "Levels of pro-inflammatory cytokines, IL-6 and IL-8, and anti-apoptotic protein, XIAP were measured by real-time PCR whereas the secreted IL-8 was quantitated by ELISA in TLR4-transient knockdown cancer cells with or without CpdA treatment." (PMID 29486738, 2018).
cancer (continued). "It is known that survivin, Mcl-1, XIAP, and cIPA2 are strongly involved in treatment resistance of PDAC; survivin and Mcl-1 play important roles in cancer stem cell (CSC) drug resistance and function." (PMID 30285798, 2018). "Several cancers have acquired resistance to interleukin-mediated apoptosis primarily because of reduced TRAIL-R1/-R2 expression, the over-expression of anti-apoptotic proteins like XIAP and c-FLIP, or elevated TRAIL decoy receptors TRAIL-R3/R4." (PMID 29522451, 2018). "These FL118 efficacy results are consistent with our molecular-targeting data showing that FL118 inhibited the expression of multiple antiapoptotic proteins (survivin, Mcl-1, XIAP, cIAP2) and ERCC6, a critical regulator of DNA repair, in treatment-resistant pancreatic stem-like cancer cells." (PMID 30285798, 2018). "It included a number of genes with obvious cancer relevance including CD44, catenin b1 (CTNNB1), vimentin (VIM), cathepsins B and S (CTSB, CTSS), MMP9, XIAP, JunD, numerous proto-oncogenes (REL, YES, SET, FGR, CRK), and HSP90AA1 (which is a chaperone which stabilizes MIF as a client)." (PMID 28957348, 2017). "Data supporting the involvement of XIAP in TRAIL resistance suggests that neutralizing XIAP might be critical for TRAIL sensitivity and an attractive target for potential combinatory therapy in the treatment of ‘type 2’ cancer cells." (PMID 28424988, 2017). "In our cohort, both survivin and XIAP were uniquely expressed in carcinoma tissue, when compared to non-neoplastic thyroid tissue specimens." (PMID 28900184, 2017). "IRES activities of XIAP, NRF, and RRBP1 in two cancer cell lines exhibited completely differently." (PMID 27447629, 2016). "ROC curve analysis for XIAP mRNA expression levels did not reveal discriminatory power in distinguishing cancer from normal tissues (AUC = 0.556; 95%CI = 0.485–0.626; p = 0.168)." (PMID 27827395, 2016). "The role of BMP signaling in regulating XIAP and TAK1 in cancer cells is poorly understood." (PMID 27048361, 2016). "The regulation of XIAP and TAK1 by the BMP signaling cascade in cancer cells is poorly elucidated." (PMID 27048361, 2016). "We measured and compared the growth rate of cancer cells that were stably transfected with XIAP IRES with those transfected with XIAP non-IRES." (PMID 25888903, 2015). "Further, we also found the down regulation of anti-apoptotic molecules BCL-2, Bcl-xL, cIAP2, XIAP, Axin2 and Survivin in the AKAP4-depleted CRC cells indicating that AKAP4 may be potential therapeutic target in cancer management." (PMID 26590805, 2015). "In many cancer cells as XIAP levels increase Smac levels do not mirror this pushing the cells into a more anti-apoptotic state." (PMID 26071313, 2015). "But if SMAC is not able to down-regulates XIAP, there will be less apoptosis and so more chances of cancer." (PMID 25707537, 2015). "For instance, targeting cIAP1/2 and/or XIAP by Smac-mimetics alone did not induce cell death in most cancer cell lines, but rather only enhanced apoptosis and cell sensitivity to chemotherapeutics and radiation." (PMID 25071009, 2014). "One possible explanation for the discrepancy of our results and previous studies might be due to the interaction between XIAP and AKT was in specific histologic types of cancer or in cell line specific pathways." (PMID 24874286, 2014). "The main challenge in the use of XIAP as a biomarker and therapeutic target is that, although XIAP is found overexpressed in many cancer tissues, its expression is not always correlated with adverse clinical outcome." (PMID 25120954, 2014).
cancer (continued). "HDACI sensitize cancer cells towards TRAIL and several mechanisms, like upregulation of TRAIL and TRAIL receptors, downregulation of c-Flip, XIAP or members of the anti-apoptotic bcl2 family members as well as the modulation of NF-κB activity were shown to contribute." (PMID 20398369, 2010). "In the context of cancer therapy, this dual role holds promise because it suggests that therapies aimed at enhancing ARTS function or mimicking its activity could simultaneously downregulate XIAP and Bcl-2, two critical anti-apoptotic proteins." (PMID 40841912, 2025). "Because the formation of XIAP :p19/p12-CASP7 impairs STS-induced apoptosis in MCF-7 cells, we wondered if blocking XIAP:p19/p12-CASP7 could enhance the efficacy of STS in CASP3/DR cancer cells." (PMID 40533441, 2025). "Previous studies have shown that the reduction in XIAP either does not occur or takes place at later time points in various cancer cell models, several hours after robust apoptosis induction, suggesting that the degradation of XIAP is not required for apoptosis induction by Smac mimetics." (PMID 37594275, 2023). "As PANC-1 cancer cells have higher nuclear factor-κB (NF-κB) and XIAP levels, antiNF-κB p65 siRNA could downregulate p65 protein and XIAP protein but not to a satisfying level." (PMID 35652096, 2022). "In order to better understand how variation in cancer cell populations can affect TRAIL sensitization via increased intracellular calcium concentrations, heterogeneous cell populations were simulated by running the model with randomly distributed cytosolic Bcl-2 and XIAP concentrations." (PMID 36080197, 2022). "Taken together, we speculate that there is an Lnc SNHG5/ miR-181-5p /XIAP axis in DLBC cells, and SNHG5 can serves as onco-LncRNA to regulate the development of DLBC, which in turn promote the proliferation and migration of the cancer cells." (PMID 35154447, 2022). "Furthermore, in certain cancer cells the absence of XIAP, cIAPs, death receptor stimulation, and treatment with Smac mimetics results in formation of a ripoptosome complex." (PMID 32182843, 2020). "However, it is worth noting that cIAP2 knockdown, but not cIAP1 or XIAP knockdown, sensitized cancer cells to apoptotic cell death induced by SMs." (PMID 32325691, 2020). "Regardless of the different phenotypes of the two cancer cell types, T3 decreased the levels of anti-apoptotic proteins (cIAP1, cIAP2, XIAP, cFLIP and Mcl-1) for a short period of exposure and altered the splicing of the anti-apoptotic MCL1L and CFLAR isoform in A2780 and HCT116 cells." (PMID 33064779, 2020). "Indeed, exceptionally only XIAP overexpression, not cIAP1/2 or Smac up and down regulation respectively, is the apoptosis resistance mechanism which can be developed in cancer cells in response to the chemotherapeutics." (PMID 31553717, 2019). "Additionally, the IAPs were detected by western blotting, and the results showed that the bacterial prodigiosin significantly decreased the expressions of XIAP and cIAP1&cIAP2 protein in the JEG3 and PC3 cancer cells as compared to the control group cells (p < 0.05)." (PMID 30400387, 2018). "Furthermore, it is not known whether the BMP and TGFβ signaling cascades cooperate to regulate XIAP and TAK1 in cancer cells." (PMID 27048361, 2016). "While XAF1 expression in tumor cells is generally very low, quantities of alternatively spliced truncated isoforms lacking the XIAP interaction have been found to increase in some aggressive cancers and have been suggested as potential biomarkers of disease status." (PMID 27613060, 2016). "Because binding of XIAP IRES to the MDM2 RING protein inhibited MDM2 homodimerization, which resulted in inhibition of MDM2 self-ubiquitination, we evaluated the cellular consequences of XIAP IRES-mediated inhibition of MDM2 self-ubiquitination in cancer cells." (PMID 25888903, 2015).
cancer (continued). "Our studies including previous one identify the binding between the MDM2 RING domain and XIAP IRES RNA that simultaneously increases expression of XIAP and MDM2, which provides an excellent molecular target to develop an alternative/innovative strategy for cancer therapeutics." (PMID 25888903, 2015). "Interestingly, SM-164 compound was shown to decrease cIAP1 expression and to prevent XIAP binding to caspases without affecting XIAP expression, further stressing the point on a cancer line specific regulation of IAPs upon SMAC mimetic treatment." (PMID 26383618, 2015). "Preliminary in vitro experiments confirm that UDCA can induce cancer cell apoptosis by promoting caspase-3, caspase-8, caspase-9, Bax, Fas/FasL, TRAIL, DR4, DR5 and IκB-α gene expression in cancer cells, and reduce the expression of Bcl-2, Bcl-xL, XIAP, cIAP-1, cIAP-2, survivin and NF-κB." (PMID 25951128, 2015). "The initial discovery of embelin as an inhibitor of XIAP by virtue of its interaction with the BIR3 domain and its observed selectivity towards cancer cells as compared to the normal cells inspired us to consider it as a lead compound for further studies against cancer." (PMID 24466324, 2014). "The aim of this study was to delineate possible differences in the anchorage-independent growth regulating behavior of XIAP protein lacking of BIRs or RING domain in order to more clearly explain their contribution to the synergistic or antagonistic effects on regulating cancer cell growth." (PMID 25216527, 2014). "One of the integral hallmarks of cancer is cancer cell survival, and curcumin is able to block this via a number of molecules with a clear involvement in survival mechanisms, several of which are NF-κB dependent such as cFLIP, BCL-xL, BCL-2, XIAP, CIAP1, CIAP2, and surviving." (PMID 24278738, 2012). "The results of anti-cancer activity experiment showed that this compound could significantly inhibit the proliferation of CNE2 cells, induce apoptosis in a dose dependent manner, and could significantly enhance the activity of XIAP." (PMID 20714320, 2010). "Therefore, in the context of caspases in cancer, we will only focus on XIAP and not discuss potential roles of the other IAPs which have been described to be overexpressed in various cancer types." (PMID 24281211, 2010). "Although, MLH1 proteolysis corresponded with a decrease in inactive procaspase-9 and an increase in caspase-3 in the cell-death response to XIAP inhibition, it would be important to determine whether MLH1 is indeed a direct substrate of caspases in cancer cells." (PMID 19603033, 2009). "This functional link between MLH1 and XIAP suggests that XIAP status may influence the effectiveness of MLH1-dependent responses to chemotherapy and that an inhibition of XIAP, in particular in MLH1-proficient cancers, may improve the CR of EOC patients to chemotherapy." (PMID 19603033, 2009). "Therefore, while CBD may modulate apoptosis, the role of XIAP in this process requires careful consideration, as its upregulation could potentially contribute to cancer cell survival rather than promoting apoptosis." (PMID 40363754, 2025). "The factors/mechanisms regulating XIAP in CRC remain poorly characterized even though indirect evidence suggests that intracellular pathways (e.g., NF-kB and STAT3), which are highly activated in CRC cells and involved in cancer cell metastasis, could up-regulate XIAP expression." (PMID 39001432, 2024).